ALDH2 (aldehyde dehydrogenase 2 family member)
Diseases named in the same sentence as ALDH2 in open-access papers (continued):
Sharing a sentence is not in itself a finding about the gene and the disease.
Alzheimer disease (42 papers, 2008 to 2024). A progressive, neurodegenerative disease characterized by loss of function and death of nerve cells in several areas of the brain leading to loss of cognitive function such as memory and language. "In fact, deficiency in the ALDH2 enzyme increases the risk for late-onset Alzheimer’s disease and cancer in multiple organs in several populations." (PMID 38891060, 2024). "Recently, this ALDH2 mutation has been reported as a risk factor for late-onset Alzheimer’s disease, potentially via a buildup of reactive oxidative species." (PMID 37839702, 2023). "Recent meta-analyses support the relationship between this ALDH2 polymorphism and Alzheimer’s disease (AD)." (PMID 37693648, 2023). "Accordingly, ALDH2*2 was demonstrated to be a risk factor for Alzheimer’s disease especially in East-Asians." (PMID 37693644, 2023). "The ALDH2 polymorphism, which can result in low activity of ALDH2, is related to susceptibility to late-onset Alzheimer's disease." (PMID 35757504, 2022). "For instance, ALDH2*2 mutation was previously demonstrated to be a risk factor for Alzheimer’s disease." (PMID 36819480, 2022). "Studies have also exhibited that ALDH2-deficient individuals not only exhibit a higher risk towards cardiovascular diseases, but also Alzheimer’s disease." (PMID 35268685, 2022). "Together, the present study provides a possible link between ALDH2 inactivating mutation and chronic excessive ethanol intake as potential contributors to Alzheimer’s disease progression." (PMID 31829281, 2019). "As reviewed, multiple epidemiological studies have identified ALDH2*2 mutation as a risk factor for Alzheimer’s disease." (PMID 31829281, 2019). "While the experiments were performed in a limited number of patient samples, these data suggest that loss of functional ALDH2 increases the vulnerability of these human fibroblasts to the Alzheimer’s disease phenotype." (PMID 31829281, 2019). "ALDH2 has also been implicated in numerous age-related pathologies, such as ischemic heart disease, Alzheimer’s disease, and Parkinson’s disease." (PMID 31209184, 2019). "Recent meta-analysis demonstrated the potential link between ALDH2*2 mutation and Alzheimer’s Disease (AD)." (PMID 31829281, 2019). "The current consensus is that the ALDH2*2 variant is a risk factor for Alzheimer’s disease, Parkinson’s disease, cardiac ischemia, stroke, and osteoporosis." (PMID 28474171, 2017). "A common polymorphism in ALDH2 gene (ALDH2*2) results in inactivation of the enzyme and is associated with alcohol flushing syndrome and increased risk for cardiovascular and Alzheimer’s diseases and some cancers." (PMID 28431562, 2017). "Evidence suggests that ALDH2 Glu504Lys SNP is a potential candidate genetic risk factor for a variety of chronic diseases such as cardiovascular disease, cancer, and late-onset Alzheimer's disease." (PMID 26491656, 2015). "A loss of function polymorphism in ALDH2 has been reported to be a risk factor for Alzheimer's disease." (PMID 22384032, 2012). "In humans, a common loss of function genetic polymorphism (ALDH2*2) frequently found in northeast Asians, has been identified as a risk factor for Alzheimer's disease." (PMID 22384032, 2012). "In East Asian populations, the prevalence of the ALDH2 rs671 variant is 30–50%, making the National Human Brain Bank for Development and Function (the largest brain bank in East Asia) an important resource to explore the link between the ALDH2 rs671 polymorphism and Alzheimer’s disease pathology." (PMID 38519490, 2024). "Recently, numerous studies focused on exploring whether ALDH2 rs671 polymorphism elevates the risk of Alzheimer’s disease (AD)." (PMID 38519490, 2024). "Moreover, a case-control study from Japan indicated that ALDH2*2 was associated with late-onset Alzheimer’s disease." (PMID 37693644, 2023).
Alzheimer disease (continued). "Approximately 40% of East Asians, accounting for 8% of the human population, carry the E504K mutation in ALDH2 that leads to accumulation of toxic reactive aldehydes and increases the risk for cardiovascular disease, cancer, and Alzheimer disease, among others." (PMID 34228649, 2021). "Recent literature suggested that ALDH2 mutation is associated with alcohol metabolism, and ethanol intake might jointly increase the risk of Alzheimer’s disease (AD) in mice." (PMID 35368830, 2021). "However, daily ethanol exposure is neurotoxic, loss of functional ALDH2 further increases the vulnerability of mice brains to these time-dependent injuries, increasing also Alzheimer’s disease-associated toxic proteins, Aβ and phosphorylated tau." (PMID 31829281, 2019). "We hypothesized that the beneficial effects of ALA on patients with Alzheimer's disease may be associated with accelerated ALDH2-mediated FA detoxification and clearance." (PMID 29249928, 2017). "It was mapped to ALDH2 by eQTL mapping approach in GTEx Whole Blood, brain nucleus accumbens basal ganglia and artery aorta tissues whose inactivating mutation has been linked to chronic excessive ethanol intake as potential contributors to Alzheimer's disease progression." (PMID 36684006, 2022). "The polymorphism was also identified as a contributor to Alzheimer’s disease progression, as risk factors, such as mitochondrial dysfunction, oxidative stress, and increased aldehyde levels in the brain, are found at greater levels in ALDH2-mutated mice compared with those in wild-type mice." (PMID 36335382, 2022). "Decreased ALDH2 activity also lowers inflammatory factor secretion, as well as amyloid β phagocytosis and spread in brains of patients with Alzheimer’s disease." (PMID 38519490, 2024). "Recent studies have shown the potential role of aldehyde dehydrogenase 2 (ALDH2) in Parkinson’s disease (PD) and Alzheimer’s disease (AD)." (PMID 39290715, 2024). "ALDH2*2 overexpressing mice are precise models of late-onset (sporadic) Alzheimer’s disease, while ALDH2–/– mice are precise models of early-onset (familiar) Alzheimer’s disease." (PMID 37693644, 2023). "In the following chapter, we will focus on hydroxynonenal and discuss ALDH2 gene transgenic and knock-out mice as precise models of Alzheimer’s disease." (PMID 37693644, 2023). "Enhancing ALDH2 activity to detoxify hydroxynonenal emerges as a promising strategy for preventing and treating Alzheimer’s disease." (PMID 37693644, 2023). "Researchers found that ALDH2 inhibits Alzheimer's disease-induced myocardial injury by regulating lipid peroxidation and ACSL4-dependent ferroptosis." (PMID 36820405, 2023). "For example, aldehyde dehydrogenase 2 family member (ALDH2) ameliorated cardiac systolic dysfunction in an amyloid precursor protein (APP)/presenilin 1 (PS1) murine model of Alzheimer’s disease by inhibiting ACSL4-dependent ferroptosis." (PMID 37372148, 2023). "A recent study reported that fibroblasts of a patient with Alzheimer’s disease (AD) had approximately 25% ALDH2 activity relative to the fibroblasts of a healthy subject." (PMID 34680107, 2021). "We also report that in mice with aldehyde dehydrogenase-2 (ALDH2) knockout, formaldehyde accumulation due to hypofunctional ALDH2 impairs memory, consistent with observations of Alzheimerʼs disease patients." (PMID 31815201, 2019). "In a model of Alzheimer’s disease, Aldh2 (−/−) mice showed age-related memory deficits in the novel object recognition and Y-maze tasks and a decrease of hippocampal synaptophysin levels." (PMID 29132299, 2017). "An initial case–control study in Japan suggested that people with an ALDH2*1/*2 or ALDH2*2/*2 genotype had a greater tendency to develop late-onset Alzheimer’s disease." (PMID 28474171, 2017). "Epidemiological studies have linked ALDH2 Glu504Lys SNP with increased risk for human diseases including cardiovascular disease (CVD), cancer, and late-onset Alzheimer's disease (AD)." (PMID 26491656, 2015).
Alzheimer disease (continued). "ALDH2 is also reported to be neuroprotective against various neurodegenerative diseases such as Alzheimer’s disease and Parkinson’s disease, possibly by removing highly reactive and cytotoxic lipid aldehydes such as 4-hydroxynonenal (4-HNE), malondialdehyde (MDA), and ACR." (PMID 38891060, 2024). "We speculate that downregulation of ALDH2 and concomitant increase in hydroxynonenal may occur in the chronic, mild ischemia of the brain at the subclinical stage of Alzheimer’s disease." (PMID 37693644, 2023). "Recent meta-analysis suggested a link between ALDH2*2 and Alzheimer’s disease." (PMID 37693644, 2023). "We speculate that Ca2+ channel blocking, combined with hydroxynonenal detoxification by ALDH2 activation, may be a more relevant therapeutic strategy for Alzheimer’s disease, compared to the cathepsin inhibition." (PMID 37693644, 2023). "Screening 20 AD patient-derived fibroblast lines, we identified ALDH2*2/*1 (heterozygote) carrier in one Japanese patient afflicted with Alzheimer’s disease (AG11369; onset at ~ the age of 50 years), who had three siblings affected with dementia (AG10643, AG10644, and AG10646)." (PMID 31829281, 2019). "In contrast with the Aldh2-knockout mice, which have no ALDH2 enzyme activity and display age-related cognitive impairment and Alzheimer’s disease, mice carrying the Glu504Lys variant do not show any abnormalities in the nervous system and are more representative of clinical scenarios." (PMID 39226171, 2024). "So, it is not surprising that many authors have shown that ALDH2 polymorphisms may be associated with the risk of the most common neurodegenerative disorders that are Alzheimer’s disease (AD) and PD." (PMID 34940794, 2022). "The finding of a Japanese woman with three siblings clinically affected with a likely non-Apo E genetic form of Alzheimer’s disease as a heterozygous carrier of ALDH2*2 mutation is consistent with our hypothesis on the role of ALDH2 insufficiency and the resulting aldehydic load on AD." (PMID 31829281, 2019). "Moreover, mice lacking ALDH2 exhibit endothelial dysfunction, age-related cognitive impairment and Alzheimer's disease." (PMID 27070252, 2016).
coronary artery disease (42 papers, 2010 to 2026). "The relationship between ALDH2 gene polymorphism and coronary artery disease (CAD) is controversial." (PMID 41551908, 2026). "Our study found that the distribution of the ALDH2 G-to-A mutation in patients with coronary heart disease varies significantly between northern and southern China, as well as between eastern and northern China." (PMID 40979589, 2025). "The ALDH2 Glu504lys polymorphism is widely considered as a risk factor for the development of coronary artery disease, especially in Asian populations." (PMID 36782330, 2023). "Study has shown that individuals with ALDH2 rs671 G/A or A/A genotype have a higher coronary artery disease (CAD) risk than individuals with G/G genotype." (PMID 37355582, 2023). "ALDH2 genetic polymorphisms have been also linked with an increased risk of type 2 diabetes in patients with coronary artery disease." (PMID 36991398, 2023). "ALDH2 rs671 A allele are associated with coronary artery disease in Chinese patients with hypertension." (PMID 32107439, 2020). "Polymorphisms in ALDH2 rs671 are associated with coronary artery disease (CAD) in Chinese patients with hypertension." (PMID 32107439, 2020). "Previous studies showed that the ALDH2 genetic polymorphism plays an important role in several pathological conditions, including hepatitis, certain types of carcinomas, coronary artery disease, cerebral infarction." (PMID 28894224, 2017). "Previous studies demonstrated that aldehyde dehydrogenase 2 (ALDH2) rs671 polymorphism, which eliminates ALDH2 activity down to 1%-6%, is a susceptibility gene for coronary disease." (PMID 27191745, 2016). "The ALDH2 *2 allele was associated with the strongest risk of coronary heart disease in a Japanese genome-wide association study (OR 1.43 [95% CI 1.35–1.51])." (PMID 26599441, 2015). "Paradoxically, some studies have also reported that the ALDH2 rs671 polymorphism was unrelated to an increased risk of coronary heart disease and myocardial infarction." (PMID 25313998, 2014). "Moreover, polymorphisms in the ALDH2 gene are associated with the occurrence and progression of coronary artery disease." (PMID 40979589, 2025). "Several studies indicate that ADH and ALDH2 variants may play an important role in the development of coronary artery disease (CAD) and MI." (PMID 41517547, 2025). "We illustrate first in detail the association between ALDH2 and coronary artery disease." (PMID 36782330, 2023). "ALDH2 is involved in oxidative and reductive reactions in vascular endothelial cells and reduced ALDH2 activity is associated with the acquisition of an early aging phenotype of endothelial cells, atherosclerosis, and coronary artery disease." (PMID 37693648, 2023). "These genes included Cdh13 and Lpl from Cluster 1; Nfia, Col4a1 and Serpinh1 from Cluster 2; Arhgef12, Col4a2, Scarb1 and Cst3 from Cluster 3; Pecam1 and Aldh2 from Cluster 4, providing plausible molecular basis for the inextricable causal link between age and coronary artery disease." (PMID 35615560, 2022). "Moreover, it has been shown that the ALDH2 Glu504Lys variant attenuates bioconversion of nitroglycerin, thus reducing its therapeutic effect on coronary artery disease." (PMID 36939783, 2021). "Both aldehyde dehydrogenase 2 (ALDH2) rs671 polymorphism and lifestyle behaviors are involved in coronary artery disease (CAD), while the interaction between them is currently unknown." (PMID 29960587, 2018). "The ALDH2*2 polymorphism (E487K) reduces ALDH2 enzyme activity, leading to a loss of its cardioprotective effects and increasing susceptibility for coronary artery and ischemic heart disease." (PMID 28883014, 2017). "Furthermore, a genome-wide association study demonstrated that an ALDH2 single-nucleotide polymorphism (SNP) (rs671) was strongly associated with coronary artery disease in a Japanese population." (PMID 26599441, 2015).
coronary artery disease (continued). "Interestingly, both BRAP and ALDH2 were found to be associated with coronary artery disease in the Japanese." (PMID 24454952, 2014). "The objectives of this study is to investigate the correlation between genotype polymorphism of aldehyde dehydrogenase 2 (ALDH2) and coronary artery disease (CAD) in atrial fibrillation patients." (PMID 41551908, 2026). "Therefore, patients with coronary heart disease and ALDH2 gene mutation might to be at greater risk of CI-AKI and renal IRI." (PMID 34228649, 2021). "Clinical studies have shown that there is a significant negative correlation between the severity of atherosclerotic plaque and the activity of Aldehyde dehydrogenase 2 (ALDH2) in patients with coronary heart disease." (PMID 36910525, 2023). "ALDH2 has been shown to be essential for tolerance to hypoxic conditions, and it plays a protective role in hypoxia-related diseases such as ischemic heart disease and hypoxic pulmonary hypertension." (PMID 36939783, 2021). "Several studies indicate the mitochondrial Aldehyde Dehydrogenase‐2 (ALDH2) gene G487A polymorphism may be correlated with coronary artery disease (CAD) susceptibility, but a clear consensus has yet to be reached." (PMID 29278292, 2018). "Recent evidence has indicated a key role for mitochondrial aldehyde dehydrogenase (ALDH2) in a wide array of heart diseases including ischemic heart disease, dilated cardiomyopathy, alcoholic cardiomyopathy, diabetic cardiomyopathy, and cardiac aging." (PMID 27634872, 2016). "ALDH2 may have beneficial cardiovascular outcomes for cardiac hypertrophy, heart failure, myocardial I/R injury, reperfusion, arrhythmia, coronary heart disease and atherosclerosis." (PMID 36910525, 2023). "Studies have shown that acetaldehyde dehydrogenase ALDH2, as a key enzyme in alcohol metabolism in human body, may affect the occurrence and development of coronary heart disease by affecting the level of blood glucose metabolism." (PMID 36762111, 2023). "Moreover, the reduced activity of the mitochondrial ALDH2 causes accumulation of acetaldehyde and 4-hydroxy-2-nonenal (4-HNE) and decrease the anti-oxidative stress effects, which has been proposed to be potentially linked with coronary artery disease (CAD)." (PMID 32160861, 2020).